RUNX2 (RUNX family transcription factor 2)
Diseases named in the same sentence as RUNX2 in open-access papers (continued):
Sharing a sentence is not in itself a finding about the gene and the disease.
hyperphosphatemia (11 papers, 2012 to 2025). Abnormally high level of phosphate in the blood. "Hyperphosphatemia and hypercalcemia lead to increased calcium and phosphate deposition in blood vessels, triggering RUNX2 expression in VSMCs, which then adopt an osteoblast-like phenotype." (PMID 37373164, 2023). "Surprisingly, hyperphosphatemia repressed the expression of RUNX2, suggesting that this model produces a pattern of HASMC trans-differentiation that is significantly different from that induced by uremia." (PMID 29483881, 2018). "In response to hyperphosphatemia, inflammation, and oxidative stress, VSMCs lose their contractile phenotype and adopt osteoblast-like features, driven by transcription factors such as Runx2, BMP2, and Msx2." (PMID 41470171, 2025). "In vitro studies have shown that hyperphosphatemia induces a phenotypic transformation of vascular smooth muscle cells into osteoblast-like cells that express biochemical markers characteristic of the bone lineage, such as Runx2, leading to calcification." (PMID 22590632, 2012). "In this review, we have discussed the regulatory roles of hyperphosphatemia, BMP2 and RUNX2 in the progression of vascular calcification." (PMID 39308809, 2024). "Hyperphosphatemia induces calcification by upregulating mRNA expression for osteogenic factors including BMP 2, Runx2/Cbfα1, Msx2, and osteocalcin." (PMID 25136676, 2014). "In summary, hyperphosphatemia can be seen as the initiating factor in a series of regulatory mechanisms during the VC process secondary to CKD, mediating the expression of BMP2 and RUNX2, which are crucial molecules affecting the VC process." (PMID 39308809, 2024).
breast tumor (10 papers, 2011 to 2024). "A strong positive association was shown for RUNX2 expression and both estrogen and progesterone receptors in G2 grade breast tumors, and there was a significant difference between G2 grade and G1/G3 grades (a higher tumor grade means less differentiated cells within the tissue specimen)." (PMID 26404249, 2015). "Because the transcription factors Oct-1/Runx2 and C/EBPβ display differential binding to these SNP alleles in epithelial breast tumor cells, it will be interesting to study this in other cell types constituting breast tumor stroma." (PMID 21767389, 2011). "BRCA1 controls the expression of miR-155 at the epigenetic level, which, in turn, directly regulates FOXO3a and RUNX2, affecting the metastatic potential of breast tumor cells." (PMID 36551878, 2022). "During this process, breast tumor cells acquire osteoblastic properties, including the expression of osteoblastic transcription factors (such as RUNX2) and osteoblastic proteins (such as osteocalcin), which are involved in microcalcification and bone matrix formation." (PMID 39684779, 2024). "This hypothesis is supported by the significant number of histopathological studies demonstrating altered expression of mineralisation associated proteins including BMP2, osteopontin, RUNX2, and TRPM7 in breast tumours with associated microcalcifications." (PMID 30679450, 2019). "On the other hand, another study showed elevated RUNX2 expression in all tumor subtypes, but its highest level was found in HER2/ErbB2 positive tumors and a significant poor prognosis was associated with the ER-negative subtype of breast tumor." (PMID 26404249, 2015). "Finally, eIF4E might confer tamoxifen resistance via oestrogen receptor independent pathway due to the activity of mTOR and MNK1, one of the downstream modulators being RUNX2 which is found to be important in breast tumour growth and metastasis." (PMID 32066877, 2020).
cervical cancer (10 papers, 2015 to 2025). A primary or metastatic malignant neoplasm involving the cervix. "For instance, in cervical cancer, high RUNX2 expression correlates with poor prognosis, and both RUNX2 and its inhibitory counterpart, miR-218-5p, are identified as potential prognostic markers." (PMID 38430423, 2024). "Previous studies have shown that RUNX3 is a tumor suppressor in cervical cancer, and we found that expression of RUNX2 and RUNX3 decreased in cervical cancer cells compared to controls." (PMID 39672307, 2024). "RUNX2 protein was detected in cervical cancer tissues, and RUNX2 expression declined upon overexpression of miR-218-5p in C-33A and CaSki cells." (PMID 37108164, 2023). "Runt related transcription factor 2 (RUNX2) can activate genes provoking tumorigenesis and metastasis, the overexpression of IL-37 in human cervical cancer cells was validated to negatively regulate their invasion by inhibiting RUNX2 at both mRNA and protein levels." (PMID 37928545, 2023). "Moreover, network analysis showed that almost all genes that interacted with YAP, including other YAP-associated transcriptional factors such as ERBB4, Runx1, and Runx2, are up-regulated in various degrees in examined cervical cancer cases." (PMID 26417066, 2015).
chondrosarcoma (10 papers, 2010 to 2025). A malignant cartilaginous matrix-producing mesenchymal neoplasm arising from the bone and soft tissue. "In chondrosarcoma, IL-1β has been found to regulate p38, which in turn promotes RUNX2-mediated MMP-13 transcription and translation, playing a crucial role in tumor progression." (PMID 40386045, 2025). "Runx2 is required for chondrogenic differentiation at later stages, maintaining the characteristic morphologies of mesenchymal chondrosarcoma." (PMID 37212282, 2023). "RUNX2 plays a key role in osteochondrogenic differentiation, and it is commonly expressed in mouse mesenchymal chondrosarcoma." (PMID 37212282, 2023). "Notably, SOX4 and runt related transcription factor 2 (RUNX2), which are both implicated in regulation of chondrogenesis and osteogenesis, are targets of miR-30a, which is progressively downregulated with increasing chondrosarcoma grade, leading to a relative overexpression of SOX4 and RUNX2." (PMID 29361725, 2018). "Runx2, which is important for differentiation and proliferation of the chondrocytic lineage, is invariably expressed in mouse mesenchymal chondrosarcoma, and interaction between HEY1-NCOA2 and Runx2 is observed using NCOA2 C-terminal domains." (PMID 37212282, 2023). "Such inhibition decreases MMP13 and Runt-related transcription factor 2 (Runx2) expression in ATDC5 chondrocyte and SW1353 chondrosarcoma cell lines." (PMID 33102472, 2020). "ICA upregulated the expression of Runx2 mRNA in the osteoblastic cell line MC3T3-E1 and treatment with ICA decreased the levels of RANK and RANKL in human SW1353 chondrosarcoma cells." (PMID 32760277, 2020). "There have been numerous studies on the anti-inflammatory effects of GPS; however, whether GPS ameliorates inflammation and chondrocyte hypertrophy in the LPS-induced SW 1353 chondrosarcoma cells via the Stat3/Runx2 signaling pathway has not been reported." (PMID 38528538, 2024). "Homozygous deletion of Runx3 exhibited growth suppression of wild-type mesenchymal chondrosarcoma cells but not Runx2-knockout cells in vitro, whereas growth property of sarcoma in vivo was not affected significantly by Runx3 knockout both in wild-type and Runx2-knockout sarcoma cells." (PMID 37212282, 2023).
non-small cell lung carcinoma (10 papers, 2007 to 2025). A group of at least three distinct histological types of lung cancer, including non-small cell squamous cell carcinoma, adenocarcinoma, and large cell carcinoma. "A pro-EMT role for the RUNX2/STK32A/NF-κB p65 axis was uncovered in non-small-cell lung cancer (NSCLC)." (PMID 37108164, 2023). "A similar result demonstrated the positive correlation of elevated RUNX2 with poor overall survival of non-small-cell lung cancer patients." (PMID 37108164, 2023). "Six transcription factors (E2F3, FHL2, ETS1, KAT6B, TWIST1, and RUNX2) were identified in the GRN as essential regulators of gene expression in non-small-cell lung cancer (NSCLC) and related to the lung tumoral process." (PMID 36551878, 2022). "Runx2 and Ezrin expressions are closely correlative to postoperative recurrence and metastasis in patients with non-small cell lung cancer." (PMID 31331331, 2019). "For instance, SNHG20 has been demonstrated to promote tumor growth through functioning as a competing endogenous RNA (ceRNA) of miR-154 in non-small cell lung cancer and modulating the expression of ZEB2 and RUNX2." (PMID 32675944, 2020).
Obesity (10 papers, 2012 to 2023). Accumulation of substantial excess body fat. "We suggest that the activation of osteogenesis and the calcification of ADSCs derived from T2DM individuals with obesity is associated with the enhanced expression of RUNX2." (PMID 35629356, 2022). "Bone and fat cells share a common origin and activation of PPARγ with diet-induced obesity is associated with decreased bone density, increased expression of PPARγ in bone, increased bone marrow adipogenesis and decreased expression of Runx2." (PMID 22260224, 2012). "This study assesses the impact of HFD on bone formation in obesity mice, demonstrating a decrease in the transcription factor Runx2, which plays a fundamental role in osteogenesis." (PMID 37529608, 2023). "The cause of decreased collagen II in knee cartilage of the 7-day male mouse offspring in the maternal obesity group was investigated by examining the collagen II-related transcription factors RUNX2 and SOX9 at the mRNA and protein levels." (PMID 35327669, 2022). "The simultaneous increase of MMPs and SMAD4-RUNX2 genes in T2D– patients with obesity is consequent, as MMP9 presents a direct target of RUNX2." (PMID 31866945, 2019). "SMAD4 and RUNX2, which are components of TGFβ signals, became the second group of genes that increased their expression in adipose tissue of T2D– patients with obesity." (PMID 31866945, 2019). "Moreover, on the contrary, RUNX2 had lower expression in T2D+ patients with obesity compared with T2D– patients with obesity." (PMID 31866945, 2019). "Moreover, RUNX2 is involved in inhibiting adipocyte differentiation and appears to be down-regulated during 3T3-L1 adipocyte differentiation and obesity reduces bone RUNX2 expression leading to bone marrow adiposity." (PMID 24040759, 2013). "MiR-197-3p and miR-23b-3p were downregulated in T2D+ patients with obesity; thus we could expect increased expression of their targets, TNFAIP6, RUNX2, and FBXL13, in these patients." (PMID 31866945, 2019). "Interestingly, EMD was able to partially compensate for the negative effects of obesity on osseous healing, osteoclast number, RUNX2 and osteopontin in this study." (PMID 34948136, 2021).
sarcoma (10 papers, 2011 to 2025). A usually aggressive malignant neoplasm of the soft tissue or bone. "We also observed that RUNX2 expression was associated with lower sarcoma patient overall survival (HR, 1.7; 95% CI, 1.14–2.53; p = 0.0086)." (PMID 36936386, 2023). "RUNX2, has been associated with survival and aggressive phenotype in sarcoma." (PMID 28061442, 2017). "In particular, the significant increase in RUNX2 protein expression in tumor samples highlights its role as a pro-oncogenic transcription factor in sarcoma development." (PMID 41141138, 2025). "In the sample of patient 25, RUNX2-positive cells increased from 60% in the primary to 90% in the sarcoma." (PMID 37686526, 2023). "Changes in RUNX2 and SATB2 expression were higher in one sarcoma, while in the other RUNX2 was decreased and SATB2-positive cells were completely lost." (PMID 37686526, 2023). "Taken together, the role of Runx3 in the differentiation of mesenchymal sarcoma was limited compared with that of Runx2, although Runx3 knockout affected cell growth in vitro." (PMID 37212282, 2023). "This sarcoma showed a low expression of RUNX2 in 10% of the nuclei of the stromal cells." (PMID 37686526, 2023). "Then, we analyzed the expression of biomarkers of osteoblasts (COL1A1, BGLAP and RUNX2), chondrocytes (COL2A1, COMP and SOX9) and sarcoma (POSTN and DCN), adipocyte (LPL and PPARG) and BMSCs." (PMID 39715773, 2024). "We detected that profound changes in morphology and the immunohistochemical profile after denosumab therapy are not compatible with changes detected in the sarcomas including expression of RUNX2, SATB2, and KI-67." (PMID 37686526, 2023).
aortic valve calcification (9 papers, 2021 to 2025). "To determine the major mechanisms underlying the effect of Runx2 depletion on aortic valve function in mice, we examined the aortic valve thickness, static aortic valve diameter, and aortic valve calcification." (PMID 34778386, 2021). "Multiple lncRNA-mediated miRNA–mRNA networks, such as the TUG-miR-204-5p-Runx2 and MALAT1-miR-191-3p-HuR networks, have been reported to be implicated in aortic valve calcification." (PMID 40937116, 2025). "In the context of aortic valve stenosis (the most common calcific aortic valve disease (CAVD) in high-income countries), RUNX2 is expressed early and is essential for the osteochondrogenic differentiation of aortic cells." (PMID 41511334, 2025). "For instance, in calcific aortic valve disease, mechanical stress sensed through the Piezo1 ion channel promotes glutaminolysis and acetyl-CoA production, enhancing H3K27 acetylation at osteogenic genes mediated by RUNX2 in valve interstitial cells." (PMID 40511385, 2025).
lung adenocarcinoma (9 papers, 2017 to 2023). A carcinoma that arises from the lung and is characterized by the presence of malignant glandular epithelial cells. "Previous studies by our research group showed that the silencing of RUNX2 in lung adenocarcinoma affected the transcriptional activation of the TWIST, SNAIL-1, and VIMENTIN genes, which also impacted the cell migration capacity." (PMID 37754231, 2023). "RUNX2 overexpression has been reported in lung adenocarcinoma (LUAD) and lung squamous cell carcinoma (LUSC)." (PMID 37754231, 2023). "In this study, we performed ChIP-seq analysis of samples of primary cultured cells from a patient with lung adenocarcinoma, and we demonstrated that the RUNX2 TF can bind to different genomic regions, such as intergenic regions, introns, and promoter regions." (PMID 37754231, 2023). "Next, we analyzed the genomic binding sites of RUNX2 via ChIP-seq analysis in primary cultured cells from a patient with lung adenocarcinoma." (PMID 37754231, 2023). "We found a critical contribution of the RUNX2 TF in transcriptional repression of TALAM1 in lung adenocarcinoma." (PMID 37754231, 2023). "We performed ChIP-seq analysis in tumor samples of a patient diagnosed with lung adenocarcinoma, and we reported the enrichment of RUNX2 in the promoters of genes such as BZW1, CARMIL1, FLOT1, and TALAM1." (PMID 37754231, 2023). "Real-time RT-qPCR was performed to quantify RUNX2 expression in the lung adenocarcinoma cell line A549 and in tumoral tissue obtained from one lung adenocarcinoma patient (LuCa)." (PMID 36510562, 2022). "Recent studies by our research group have revealed that the overexpression of RUNX2 in lung adenocarcinoma is involved in epithelial-mesenchymal transition through transcriptional regulation of the VIMENTIN, TWIST1, and SNAIL1 genes." (PMID 36510562, 2022). "As a follow-up to this work, the authors recommend performing RUNX2 gain-of-function studies in our biological model of lung adenocarcinoma to confirm the findings presented above." (PMID 36510562, 2022). "To identify the role of the RUNX2 transcription factor in the apoptosis process in lung adenocarcinoma cells, we knocked down RUNX2 using sh-RNA in A549 cells." (PMID 36510562, 2022). "In addition, we performed shRNA-mediated knockdown of RUNX2 in this lung adenocarcinoma cell line to confirm the regulatory role of RUNX2 in TALAM1 expression." (PMID 37754231, 2023). "Together, these results indicated that the RUNX2 TF might participate in the transcriptional control of TALAM1 in lung adenocarcinoma." (PMID 37754231, 2023). "We next investigated whether TALAM1 transcription in A549 lung adenocarcinoma cells is modulated by the transcription factor RUNX2, which was observed to bind to the TALAM1 promoter region." (PMID 37754231, 2023). "In our laboratory, RUNX2 has been related to the positive regulation of gene expression associated with EMT, such as vimentin and SNAIL1, thereby increasing the migratory capacity of lung adenocarcinoma cells." (PMID 36551878, 2022). "RUNX2-depleted cells exhibited higher TALAM1 levels, suggesting that the RUNX2 TF promotes transcriptional repression of TALAM1 in lung adenocarcinoma." (PMID 37754231, 2023). "RUNX2 was overexpressed in lung adenocarcinoma in a large study that included 2418 tumor and 1574 nontumor lung samples." (PMID 37108164, 2023). "Additionally, we performed shRNA-mediated knockdown of RUNX2 in a lung adenocarcinoma cell line to confirm its regulatory role in the expression of TALAM1, a long noncoding RNA (lncRNA) identified as a target of RUNX2 TF in this work." (PMID 37754231, 2023). "In summary, our results indicate that the RUNX2 transcription factor participates in the intrinsic pathway of apoptosis avoidance through the transcriptional regulation of antiapoptotic genes BCL2, BCL-XL, and MCL1 in lung adenocarcinoma." (PMID 36510562, 2022).
lung adenocarcinoma (continued). "Interestingly, among the other defective pathways in the MPM group, one (R-HSA-8941326) affects RUNX2, the master gene in osteogenesis, which has been shown to increase expression of EMT genes (included in R-HSA-8941326) vimentin, TWIST1 and SNAIL1 in lung adenocarcinoma cells." (PMID 36362413, 2022).
metastatic carcinoma (9 papers, 2011 to 2025). A carcinoma which has spread from the original site of growth to another anatomic site. "RUNX2 has been shown to participate in the regulation of mammary specific gene expression and metastatic cancer progression in established breast cell lines." (PMID 37256183, 2023). "Together these studies support the possibility of Runx2 serving a scaffolding role in microtubule dynamics in bone metastatic cancer cells." (PMID 35884497, 2022). "Among these was RUNX2, the main transcription factor of osteoblast differentiation, which has previously been found to be ectopically expressed in metastatic cancer cells." (PMID 24292404, 2014). "Several studies have indicated that Runx-2 regulates MMP-9 expression in metastatic cancer cells." (PMID 30105080, 2018). "Furthermore, it was found that Runx2 is ectopically expressed in metastatic cancer cells but not in non-metastatic cancer cells, and that several genes required for bone development and turnover, such as opn, bsp, mmp12 etc., are activated by Runx2." (PMID 21649908, 2011).
T-cell lymphoma (9 papers, 2010 to 2023). "Upregulation of RUNX2 and Pim-1 was found to synergistically promote the development of T-cell lymphoma, suggesting the phosphorylation mediated by Pim-1 has a positive effect on RUNX2′s cancer-promoting function." (PMID 36429115, 2022). "Runx2 exerts a dominant oncogenic role in T-cell lymphomas; however, little evidence about its role in primary epithelial cancers has been described." (PMID 24626992, 2014). "Interestingly, lesions were positive for MYC (n=4), which has been shown previously to act cooperatively with RUNX2 to drive T-cell lymphoma." (PMID 24626992, 2014). "Similarly the targeting of novel genes that were not seen in previous large-scale screens of MoMLV-induced T-cell lymphomas (e.g. Otx2, Myo16) is not merely due to their up-regulation in the background of the Runx2/MYC model." (PMID 24586197, 2014).